KCNQ1 (potassium voltage-gated channel subfamily Q member 1)
Diseases named in the same sentence as KCNQ1 in open-access papers (continued):
Sharing a sentence is not in itself a finding about the gene and the disease.
ischemia (1 paper, 2012). A hypoperfusion of the BLOOD through an organ or tissue caused by a PATHOLOGIC CONSTRICTION or obstruction of its BLOOD VESSELS, or an absence of BLOOD CIRCULATION. "In canine hearts infarcted for 5 days, chronic ischemia decreased IKs current density and downregulated the expression of KCNQ1 and KCNE1 mRNA." (PMID 22384037, 2012). "In this study, membrane KCNQ1 protein expression was severely depressed by chronic ischemia and moderately downregulated by transient ischemia (20 min ischemia in our protocol)." (PMID 22384037, 2012). "There have been a limited number of reports regarding the effect of ischemia on IKs amplitude and KCNQ1 expression." (PMID 22384037, 2012). "However, the effect of transient and chronic ischemia on the expression of KCNQ1 and KCNE1 proteins has not been determined." (PMID 22384037, 2012).
ischemic cardiomyopathy (1 paper, 2025). Ischemic cardiomyopathy is a cardiomyopathy in which a weakness in the muscle of the heart due to inadequate oxygen delivery to the myocardium with coronary artery disease being the most common cause. "Our study provides a novel perspective by investigating KCNQ1 gene polymorphisms in relation to ventricular tachyarrhythmia (VTA) development in patients with ischemic cardiomyopathy for the first time." (PMID 40365780, 2025). "The most notable finding of our study is that the KCNQ1 gene polymorphism independently predicts the development of VTA in patients with ischemic cardiomyopathy." (PMID 40365780, 2025). "Our findings suggests that KCNQ1 polymorphism may serve an independent predictor of VTA development in patients with ischemic cardiomyopathy." (PMID 40365780, 2025). "Our findings indicate that the KCNQ1 polymorphism may be a useful parameter in distinguishing the patients at risk for VTA from among those who developed ischemic cardiomyopathy on a scar substrate." (PMID 40365780, 2025).
melanoma (1 paper, 2022). A malignant, usually aggressive tumor composed of atypical, neoplastic melanocytes. "Although it is unclear how melanoma induces KCNE4 in lymphatic vessel endothelium, KCNE4 co-localized with KCNQ1 in LNs, suggesting that KCNE4 regulates KCNQ1 in lymphatic endothelium." (PMID 35915077, 2022).
MELAS (1 paper, 2021). "Additionally, we identified heterozygous KCNQ1 mutation c.575G > A (p.Arg192His) and heterozygous KCNQ2 mutation c.598C > A (p.Leu200Met) in one MELAS patient (P9)." (PMID 33484326, 2021).
MODY (1 paper, 2022). "Along with MODY genes, KCNQ1 mutations could influence T2DM by decreasing pancreatic β-cell mass and insulin secretion as per the present study." (PMID 35956399, 2022).
oesophageal adenocarcinoma (1 paper, 2023). "We chose to reduce the expression of KCNQ1 using a CRISPR/Cas9-induced knockout (KO) and overexpression (OE) KCNQ3 in oesophageal adenocarcinoma cell lines OE33 and FLO-1." (PMID 37748809, 2023). "KCNQ1 plays a role in colon cancer and in hepatocellular carcinoma, and KCNQ3 is hypermutated in oesophageal adenocarcinoma." (PMID 37748809, 2023).
oesophageal cancer (1 paper, 2023). "Through integration of data at the patient, cell, and protein structural levels, coupled with in vitro models, we show that KCNQ genes, specifically KCNQ1 and KCNQ3, and their protein products contribute to gastro-oesophageal cancer phenotype and are a potential therapeutic target." (PMID 37748809, 2023).
periodontal disease (1 paper, 2019). "Applying the candidate gene approach, SNPs in IL1β (rs1143634) and KCNQ1 (rs2237892) were shown to be associated with comorbidity of rheumatoid arthritis and periodontal disease." (PMID 30890897, 2019).
progeria (1 paper, 2024). "Altogether, these data identify Kcnq1 as a potential target to improve vascular function in progeria." (PMID 37233881, 2024).
sarcoma (1 paper, 2024). A usually aggressive malignant neoplasm of the soft tissue or bone. "However, other KCNQ1 variants are reported in a variety of tumor types, including 4% (33/867) of soft tissue tumors, mainly in unclassified sarcoma from fibrous tissue/uncertain origin (23/33)." (PMID 39594770, 2024). "Both germline and somatic hits were found in the ATM, CDC73, MLH1, MSH6, POLG, and KCNQ1 genes, which have no previously known connection with sarcoma." (PMID 39594770, 2024).
Sepsis (1 paper, 2021). Sepsis is defined as life-threatening organ dysfunction caused by a dysregulated host response to infection. "For instance, in myocardial damage mediated by sepsis, the competitive binding of KCNQ1 opposite strand/antisense transcript 1 (KCNQ1OT1) and miR-192-5p modulates the X-linked inhibitor of apoptosis (XIAP) expression, and KCNQ1OT1 overexpression mitigates myocardial injury stemming from sepsis." (PMID 34592882, 2021).
Stillbirth (1 paper, 2019). Death of the fetus in utero after at least 22 weeks of gestation. "Furthermore, the total number of pathogenic alleles in KCNQ1 observed in our cohort was significantly higher compared with ExAC NFE (p = 0.046), which supports that SNVs in this gene might play a role in stillbirth." (PMID 30615648, 2019).
tobacco use disorder (1 paper, 2022). "We also observed nominal associations between rare variants in KCNQ1 and substance use disorders (P = 2.4 × 10–4), and APOB and tobacco use disorder (P = 1.1 × 10–3)." (PMID 35590255, 2022).
ulcerative colitis (1 paper, 2016). An inflammatory bowel disease involving the mucosal surface of the large intestine and rectum. "We therefore evaluated KCNQ1/KCNE3 channels in distal colonic crypts obtained from normal and active ulcerative colitis (UC) patients." (PMID 26718405, 2016).
tumor (33 papers, 2011 to 2025). "Loss of KCNQ1 has been reported to exert anti‐tumor functions via promoting epithelial‐to‐mesenchymal transition (EMT) and disrupting adheren junctions in epithelial cancers." (PMID 37830163, 2024). "In this study, we aimed to explore the significance of KCNQ1 in terms of clinical value, tumor immunity, underlying mechanisms, and a precision medicine approach by means of multi-omics analysis." (PMID 35216393, 2022). "Firstly, we analyzed the association between KCNQ1 and cancers and confirmed its tumor suppression role in LUAD." (PMID 35216393, 2022). "Based on the fact that the ESTIMATE score is inversely correlated with tumor purity, this result indicates that high KCNQ1 expression is associated with lower tumor purity, thereby influencing the immune status of the tumor microenvironment." (PMID 35216393, 2022). "KCNQ1 with altered variants had associations with favorable prognosis, while its low expression predicted worse prognosis and negatively correlated with tumor proliferation indicator Ki67." (PMID 35216393, 2022). "By studying data from varying sources simultaneously, we find consistently that KCNQ1 shows properties of a tumour suppressor—it is often deleted or lost in patients, mutations are generally inactivating, and cell proliferation can be increased when it is lost." (PMID 37748809, 2023). "We then asked whether KCNQ1 is associated with tumor proliferation by analyzing Pearson correlation coefficients of KCNQ1 with Ki67." (PMID 35216393, 2022). "Specifically, the inhibition of DBF4, CCNA2, CCNB1, MCM6, CDC45, CHEK1, and CDC6 may be implicated in KCNQ1-mediated tumor suppression." (PMID 35216393, 2022). "Potassium voltage-gated Channel subfamily Q member 1 (KCNQ1) is a tumor suppressor that is hypermethylated in human HCC, and KCNQ1 interacts with β-catenin inhibiting its activity." (PMID 41300975, 2025). "KCNQ1 has also been demonstrated to act as a tumor suppressor gene in some gastrointestinal cancers." (PMID 38807370, 2024). "SLC22A18 is located in 11p15.5, an important tumor-suppressor gene region, together with other 21 genes including KCNQ1 that was found within one identified significant DMR." (PMID 38424222, 2024). "KCNQ1 functions as a tumor suppressor gene that controls cellular growth, innate immunity, signaling pathways that control growth, and inflammation." (PMID 37371985, 2023). "When lost or inactive, KCNQ1 acts as a tumor suppressor, because it prevents the development of cancer." (PMID 37371985, 2023). "KCNQ1 is a gene encoding a potassium channel that is widely expressed in human and rodent tissues, and KCNQ1 functions as a tumor suppressor gene in the gastrointestinal tract of both humans and mice." (PMID 36923404, 2023). "For ACT-treated patients stratification for LVI at first, followed by expression of KCNQ1 for the LVI-negative tumours, was most informative." (PMID 35395779, 2022). "Then, the wound healing assay showed that cells treated with si-KCNQ1 had superior migration abilities compared to cells with si-control, thereby verifying the anti-tumor effect of KCNQ1." (PMID 35216393, 2022). "Our study revealed that high KCNQ1 expression intimately correlated with an immune infiltration profile that is associated with longer survival time and with downregulation of immunomodulatory genes, which may concurrently act to shape an immunoactive tumor microenvironment." (PMID 35216393, 2022). "KCNQ1 is a tumor suppressor gene in mice, and low Kv7.1 expression has been found to accelerate tumor progression and affect patient survival through analysis of tissue samples from CRC patients." (PMID 36703789, 2022). "The stabilisation of the β-catenin/E-cadherin/KCNQ1 complex at the AJ constitutes an explanation to understand the role of KCNQ1 as a tumor suppressor in CRC and HCC." (PMID 33117152, 2020). "We and other have explored this issue to identify the molecular mechanism sustaining the tumor suppressor functions of KCNQ1 in CRC and HCC." (PMID 33117152, 2020).
tumor (continued). "KCNQ1 is a tumor suppressor in CRC and its sustained expression has been linked to suppression of the Wnt/β-catenin signaling pathway that contributes to CRC tumor progression." (PMID 33363037, 2020). "In CRC, KCNQ1 is gradually becoming recognized as a key tumor suppressor." (PMID 37371985, 2023). "Thus, IC2 methylation and KCNQ1OT1 imprinting were similarly relaxed in the neoplastic and peri-neoplastic tissues and KCNQ1 was increased in the tumor of our patient." (PMID 37046605, 2023). "The mutation spectra/count of KCNQ1 was not in synchronicity with the corresponding tumor mutational burden (TMB)." (PMID 35216393, 2022). "KCNQ1 channels also act as a tumor suppressors in gastrointestinal and esophageal cancers." (PMID 36033489, 2022). "Given that KCNQ1 plays a tumor suppressive role, its downregulation may promote the proliferation and metastasis of cancer cells." (PMID 35216393, 2022). "There is preliminary evidence to suggest that KCNQ1 is a tumor suppressor in the stomach and colon." (PMID 34771544, 2021). "As we shall discuss in detail, some of these targets include pivotal estrogen-regulated cell signaling pathways including the Wnt/β-catenin pathway, ion channels acting as tumor suppressors such as the Kv channel KCNQ1, and membrane estrogen receptors such as GPER." (PMID 33363037, 2020). "The estrogen-induced release of KCNQ1 from the KCNQ1:KCNE3 complex may enhance tumor suppressor effects of KCNQ1." (PMID 33363037, 2020). "KCNQ1 regulation may represent a link between the normal physiological actions of estrogen in the colon and the hormone’s apparent tumor-suppressive effects in CRC development." (PMID 33363037, 2020). "In germinal tumours, an increase of Kv7.1 (KCNQ1) and KCNE1 subunits has been found." (PMID 25590133, 2015). "Deficiency of either Kcne2 or Kcnq1 results in achlorhydia, gastric hyperplasia, and neoplasia, but the impact on iron absorption has not, to our knowledge, been investigated." (PMID 25127743, 2014). "Therefore, they reach the same conclusion as in CRC, KCNQ1 acts as a tumor suppressor in HCC." (PMID 33117152, 2020). "We previously evaluated tumour tissue expression of 28 proteins and identified multiple biomarkers with prognostic value, such as Aurora kinase A, Lamin A/C, CDX2, KCNQ1 and MACROD2." (PMID 35395779, 2022). "There is also evidence that KCNQ1 (potassium voltage-gated channel member), MTA3, and ZSWIM5 (zinc finger SWIM-type 5) have tumor suppressive roles." (PMID 31149338, 2019). "We also find a weak but significant correlation between KCNQ1 and KCNQ3 expression and tumour stage in patient data, suggesting that this finding may be extended to human cancer." (PMID 37748809, 2023). "Additionally, the lncRNA KCNQ1OT1 regulates the imprinted expression of the KCNQ1 and CDKN1C genes, both showing tumor suppressor activity in several tumors, including CRC." (PMID 37046605, 2023). "For the subset of tumours without LVI, high expression of KCNQ1 was subsequently associated with the best survival." (PMID 35395779, 2022). "Estimation of STromal and Immune cells in MAlignant Tumor tissues using Expression data (ESTIMATE) analysis was employed to determine the stromal score, immune score, and ESTIMATE score between a high KCNQ1 group and a low KCNQ1 group in a TCGA-LUAD cohort." (PMID 35216393, 2022). "Although the KCNQ1 gene has been identified as a tumor suppressor in CRC tissues, the precise functional and molecular events linking KCNQ1 and CRC progression remain unclear." (PMID 33363037, 2020). "Supporting this, KCNQ1, CFTR and ClCN-2 have been described as tumor suppressors in CRC." (PMID 33117152, 2020). "KCNQ1 levels had a negative correlation with tumor proliferation index Ki67 levels." (PMID 35216393, 2022).
tumor (continued). "In this paper, Migdalska-Sek at al. assessed and compared the methylation level of 8 tumor suppressor genes, ARHI, CDH1, KCNQ1, MEST, p16INK4A, RASSF1A, SLC5A8 and VHL in PTC tumor tissues and matched adjacent noncancerous thyroid tissues." (PMID 25490036, 2014). "Samples where RFLPs were present in the lymphocyte DNA sample but absent or with an altered ratio in the tumor sample were considered to exhibit LOH in the regions of 8 imprinted genes (H19, IGF2, KCNQ1, LIT1, GTL2, PEG1, PEG3 and NDN)." (PMID 22443985, 2012). "However, it is important to note that IC2 methylation and KCNQ1OT1 imprinting were similarly relaxed in the neoplastic and peri-neoplastic tissues, and KCNQ1 and CDKN1C were not repressed in the tumor with respect to normal tissue in our patient." (PMID 37046605, 2023). "Concentrations of Gamitrinib that trigger tumor cell killing (IC50 ~1-4 μM) do not affect cytochrome P450 isoforms CYP1A2, CYP2A6, CYP2B6, CYP2C8 or ion channel conductance (Nav1.5, Kv4.3/KChIP2, Cav1.2, Kv1.5, KCNQ1/mink, HCN4, Kir2)." (PMID 35129069, 2022).
cancer (28 papers, 2010 to 2024). A tumor composed of atypical neoplastic, often pleomorphic cells that invade other tissues. "LncRNA KCNQ1 opposite strand/antisense transcript 1 (KCNQ1OT1) is located at the KCNQ1 cluster on human chromosome 11p15.5 and is highly associated with the development of cancer." (PMID 36291546, 2022). "Potassium voltage-gated channel subfamily Q member 1 (KCNQ1) has been found to be very prominent in the K2p channels that lead to increased cancer risk." (PMID 36060694, 2022). "Cancer patients with altered KCNQ1 variants showed significant longer overall survival, disease specific survival, and progression free survival." (PMID 35216393, 2022). "None of the hamster littermate siblings that were either wild-type or heterozygous for KCNQ1 mutations developed cancers." (PMID 35954238, 2022). "In addition, we showed that the diagnostic and prognostic value of KCNQ1 can be extrapolated to other cancer types, including KIRC, PCPG, and COAD." (PMID 35216393, 2022). "Interestingly, the key signaling molecule β-catenin involved in numerous cancers was also found recently to associate with the ion channels KCNQ1 and BKCa to modulate Wnt signaling." (PMID 30837866, 2019). "Thus, for reasons that remain unknown, the complete loss of KCNQ1 function uniquely leads to widespread blood cell cancer development in hamsters." (PMID 35954238, 2022). "Therefore, could alternative functions of this channel underlie the observed correlations between KCNQ1 expression and cancers development?" (PMID 33117152, 2020). "It was observed that the protein expression of KCNQ1 gene in 8 cancers was significantly lower than that in normal tissues." (PMID 39317949, 2024). "KCNQ1OT1/Kcnq1ot1, an lncRNA transcribed from the opposite strand of KCNQ1 within the CDKN1C/KCNQ1OT1 cluster, has been implicated as a critical factor in cancer development and progression." (PMID 39201613, 2024). "We found that most of the genes were risk factors in several cancers, except for CTLA4, KCNQ1, and GLS2." (PMID 36860371, 2023). "In metastatic adenocarcinoma, there are an almost complete loss of KCNQ1 and a concurrent up-regulation of KCNQ3, confirming that KCNQ protein levels correlate with disease severity in a model of GOA cancer." (PMID 37748809, 2023). "Based on the apparent links between KCNQ genomic status and cancer from patient data, we next sought to establish how changes in KCNQ1 and KCNQ3 expression impact cancer cell phenotype." (PMID 37748809, 2023). "Caution must thus be taken when considering therapeutic applications of KCNQ involvement in cancer, due also to the extreme importance of KCNQ1 in cardiac activity." (PMID 37748809, 2023). "Overall, >85% of the KCNQ1 homozygous KO hamsters developed cancers, with the mean age when they became moribund at 150 days." (PMID 35954238, 2022). "First, the KCNQ1 KO hamsters represented the initial creation of a genetically engineered hamster cancer model." (PMID 35954238, 2022). "The methylation levels of CpG islands of KCND3 were higher in cancer secretion groups, while the methylation levels of KCNQ1 were lower than those in control and medium groups." (PMID 35265687, 2022). "ShRNA-based knockdown of KCNQ1 was shown to promote cytosolic accumulation of β-catenin, which acts to mediate the proliferation of cancer cells." (PMID 35216393, 2022). "Adult KCNQ1 homozygous KO hamsters developed severe physical stress as early as 70 days of age, including overt cancers at necropsy." (PMID 35954238, 2022). "KCNQ1 Opposite Strand/Antisense Transcript 1 (KCNQ1OT1) encodes a lncRNA from the opposite strand of KCNQ1 in the CDKN1C/KCNQ1OT1 cluster that is reported to play a vital role in the development and progression of cancer." (PMID 34827600, 2021). "Potassium channels have emerged as a potential target for anti-cancer therapies, including KCNQ1, hERG and Kv2.1, all of which are α subunit partners of KCNE2." (PMID 20625512, 2010).